TRIM2 (tripartite motif containing 2)
Description:
UBE2D1-dependent E3 ubiquitin-protein ligase that mediates the ubiquitination of NEFL and of phosphorylated BCL2L11. Plays a neuroprotective function. May play a role in neuronal rapid ischemic tolerance. Plays a role in antiviral immunity and limits New World arenavirus infection independently of its ubiquitin ligase activity.
Synonyms: KIAA0517; RNF86; CMT2R
Tractability: Small molecule: a structure with a bound ligand is known. PROTAC: UniProt records ubiquitination sites on it; ubiquitination databases record sites on it; its protein half-life has been measured.
Gene: Protein-coding gene on chromosome 4 (153,152,163 to 153,339,319, forward strand). Ensembl gene ENSG00000109654.
Subcellular location: Cytoplasm
Subcellular location (Human Protein Atlas): Centrosome
Pathways (Reactome):
Immune System: Interferon gamma signaling
Gene Ontology:
Molecular function: protein binding; ubiquitin protein ligase activity; ubiquitin-protein transferase activity; zinc ion binding
Biological process: proteasome-mediated ubiquitin-dependent protein catabolic process; protein polyubiquitination; regulation of neuron apoptotic process; protein ubiquitination
Cellular component: cytoplasm
Genetic constraint (gnomAD): Loss-of-function variants: 18 observed, 67.07 expected, observed/expected ratio (o/e) 0.27, 90% interval 0.19 to 0.4. The upper end of that interval is the gene's LOEUF score, 0.4, which puts it in group 1 of 6, group 1 being the genes least tolerant of losing a copy. Missense variants: 640 observed, 978.42 expected, observed/expected ratio (o/e) 0.65, 90% interval 0.61 to 0.7. Synonymous variants: 357 observed, 379.72 expected, observed/expected ratio (o/e) 0.94, 90% interval 0.86 to 1.03.
Homologues: Orthologues: chimpanzee TRIM2 (99% identical), mouse Trim2 (99% identical), rabbit TRIM2 (98% identical), pig TRIM2 (98% identical), rat Trim2 (98% identical), dog TRIM2 (97% identical), guinea pig TRIM2 (95% identical), tropical clawed frog trim2 (89% identical), zebrafish trim2a (77% identical), zebrafish trim2b (60% identical). Paralogues in human: TRIM3 (65% identical), TRIM71 (31% identical), TRIM56 (22% identical), TRIM24 (18% identical), TRIM33 (18% identical), TRIM66 (16% identical), TRIM37 (15% identical), TRIM9 (14% identical), TRIM67 (14% identical), TRIM28 (14% identical), TRIM46 (13% identical), PML (12% identical), and 68 more.
Diseases named in the same sentence as TRIM2 in open-access papers:
TRIM2 is named in the same sentence as 54 diseases in open-access papers, as found by Europe PMC text mining. Sharing a sentence is not in itself a finding about the gene and the disease. The quoted sentences say what the papers report.
osteosarcoma (9 papers, 2019 to 2024). A usually aggressive malignant bone-forming mesenchymal neoplasm, predominantly affecting adolescents and young adults. "The results in this study are consistent with other studies in colorectal cancer and osteosarcoma, which similarly showed that high TRIM2 expression was associated with unfavourable clinical outcomes and metastasis promotion." (PMID 38893070, 2024). "In osteosarcoma, the E3-ubiquitin ligase TRIM2 is implicated in regulating development and metastasis, while its downregulation in clear cell renal cell carcinoma promoted cell proliferation, migration, and invasion and acted as an unfavorable prognostic indicator." (PMID 31261735, 2019). "TRIM2 in osteosarcoma reduces Bcl-2-interacting mediator (Bim) expression and causes excessive proliferation of cancer cells via the PI3K/AKT/mTOR signalling pathway." (PMID 38893070, 2024). "Many studies have reported the role of TRIM2 as a tumor promoter during progression of a majority of cancers such as osteosarcoma and breast cancer." (PMID 35342411, 2022). "After TRIM2 inhibition in osteosarcoma cell lines, the protein level of p-AKT was decreased, while the level of AKT showed no significant change." (PMID 36051486, 2022). "TRIM2 has tumor-promoting roles in osteosarcoma and colorectal cancer (PMID: 30066883, PMID: 30916596)." (PMID 34354115, 2021). "Previous study had shown that TRIM2 is differentially expressed in ovarian, cervical, follicular, and osteosarcoma tumors." (PMID 32536816, 2020). "The study indicated that the PI3K/AKT pathway may be involved in regulating TRIM2 in the development and metastasis of osteosarcoma tumour cells." (PMID 38893070, 2024). "Furthermore, recent clinical studies have identified TRIM2 as a potential oncogene in human cancer cell lines including colorectal carcinoma, epithelial ovarian carcinoma and osteosarcoma." (PMID 38542330, 2024). "A study on osteosarcoma indicated that TRIM2 may affect the proliferation, migration, and invasion of osteosarcoma cells through the PI3K/AKT signaling pathway and that high TRIM2 expression is associated with a low survival rate and promotion of metastasis." (PMID 36051486, 2022). "In a study of osteosarcoma, after TRIM2 was silenced, DDIT3 was significantly upregulated." (PMID 36051486, 2022). "However, in cervical cancer and osteosarcoma, upregulation of TRIM2 expression is consistent with this study." (PMID 32536816, 2020). "Among them are TRIM2 (up-regulated in osteosarcoma, down-regulated in kidney cancer), TRIM29 (up-regulated in lung cancer and osteosarcoma, down-regulated in liver and prostate cancers), TRIM33 (up-regulated in breast cancer, down-regulated in liver and kidney cancers)." (PMID 33673719, 2021). "In addition, the protein levels of PKA, CREB, and p-CREB were not affected upon TRIM2 inhibition in osteosarcoma cell lines, suggesting that TRIM2 regulates the progression and metastasis of osteosarcoma through the PI3K/AKT signaling pathway." (PMID 36051486, 2022). "After silencing TRIM2, all of these genes except for FZD8 and SHC2 were significantly upregulated in both cell lines, as shown by RT–PCR; therefore, it is speculated that TRIM2 can function by regulating five genes that are significantly upregulated in osteosarcoma." (PMID 36051486, 2022).
axonal neuropathy (7 papers, 2016 to 2023). Any nerve disorder affecting the axon of a nerve. "Changes in TRIM2 function have been linked to progressive neurodegeneration in Alzheimer’s patients, while its variations have been associated with childhood-onset axonal neuropathy." (PMID 38328521, 2023). "Recently, a human patient with a heterozygous missense mutation in TRIM2 was reported to exhibit a loss of gross motor neuron development that resulted in an early onset of axonal neuropathy, muscle hypotonia, and sarcopenia." (PMID 32698497, 2020). "Trim2 is an E3 ubiquitin ligase that is highly expressed in the hippocampus and deficiencies in Trim2 levels has been associated with axonal neuropathy." (PMID 32211019, 2020). "A CMTD patient with early onset peripheral axonal neuropathy was identified as a compound heterozygote for mutations in TRIM2 by whole-exome sequencing." (PMID 30726215, 2019). "Human case reports have also described loss-of-function mutations in TRIM2 causing early-onset axonal neuropathies." (PMID 29958463, 2018). "Mutations in the TRIM2 gene have been associated with childhood onset of axonal neuropathy." (PMID 32698497, 2020). "The protein expressed by the TRIM2 gene is part of the tripartite motif family that plays a role in neuroprotection, while deleterious mutations in TRIM2 are known to cause early-onset axonal neuropathy." (PMID 27812365, 2016). "TRIM2 has also been implicated in rare peripheral neuropathies in humans, part of the Charcot–Marie–Tooth diseases (CMTDs); patients lacking functional TRIM2 protein developed peripheral axonal neuropathy." (PMID 30726215, 2019).
colorectal cancer (7 papers, 2020 to 2024). A primary or metastatic malignant neoplasm that affects the colon or rectum. "It has been reported that TRIM2 plays an oncogenic role in cancer types including lung adenocarcinoma and colorectal cancer and has prognostic value." (PMID 38893070, 2024). "In other cancers, TRIM7 can suppress hepatocellular carcinoma progression, while an oncogenic function was reported in colorectal cancer and pancreatic cancer for TRIM2 and in hepatocellular carcinoma for TRIM52-AS1." (PMID 35928444, 2022). "TRIM2 also regulated the metastasis of colorectal cancer cells through EMT in vivo and in vitro." (PMID 38893070, 2024). "TRIM2 could aggravate cell proliferation, invasion, and migration in colorectal cancer by regulating Snail1 ubiquitylation degradation." (PMID 32536816, 2020). "TRIM2, TRIM28, TRIM29, TRIM59, and other TRIM family are relevant to malignancy of neurologic tumors such as glioma and digestive tumors such as gastric cancer, colorectal cancer." (PMID 33118318, 2020).
breast carcinoma (5 papers, 2021 to 2025). "Further research is needed to understand how TRIM2 functions and its connection to glutamine metabolism in breast cancer." (PMID 38893070, 2024). "To date, there have been few functional experiments investigating the relationship between TRIM2 and breast cancer." (PMID 36051486, 2022). "The expression of TRIM2 in basal-like breast carcinoma (BBC) is related to that of SOX10, and the expression of TRIM2 in breast cancer is clearly abnormal." (PMID 36051486, 2022). "GPER-MAPK/ERK pathway activation also affected the interaction of TRIM2 and Bim, leading to ubiquitination-mediated degradation of Bim, which plays a key role in the apoptosis of tamoxifen-resistant breast cancer cells." (PMID 36051486, 2022). "In a study of tamoxifen resistance, TRIM2 was found to be highly expressed in the TAM-resistant breast cancer cell line MCF-7R, while the expression of Bim was significantly decreased." (PMID 36051486, 2022). "The prognostic significance of tripartite motif-containing 2 (TRIM2) mRNA was assessed in BC transcriptomic data (n = 16,575), and TRIM2 protein expression was evaluated using immunohistochemistry (n = 749) in patients with early-stage invasive breast cancer with long-term follow-up." (PMID 38893070, 2024).
lung adenocarcinoma (5 papers, 2020 to 2024). A carcinoma that arises from the lung and is characterized by the presence of malignant glandular epithelial cells. "Three commonly used molecular drugs including docetaxel, doxorubicin, and gefitinib are used to investigate the effect of TRIM2 expression on the therapeutic sensitivity of lung adenocarcinoma cells." (PMID 36051486, 2022). "In an in vitro experiment, the proliferation, colony formation, migration, and invasion of lung adenocarcinoma cells were found to be significantly enhanced after TRIM2 overexpression." (PMID 36051486, 2022). "Research on TRIM2 can provide more detailed information for further studies on lung adenocarcinoma, including the search for biological targets." (PMID 36051486, 2022). "More experiments are needed to investigate the combined effects of TRIM2 on survival in patients with lung adenocarcinoma." (PMID 33714206, 2021). "This study showed that the expression of TRIM2 in lung adenocarcinoma tissues was higher than in adjacent tissues." (PMID 32536816, 2020). "Firstly, we had detected the expression of TRIM2 in lung adenocarcinoma tissue and the paired normal tissues with the online dataset, western blot, qRT-PCR, and immunohistochemical staining analysis." (PMID 32536816, 2020). "Meanwhile, TRIM2 can deubiquitinate and stabilize Snail1 protein, which play important role in the function of lung adenocarcinoma." (PMID 32536816, 2020). "In summary, TRIM2 expression in lung adenocarcinoma tissue was higher than those in the paired normal tissues." (PMID 32536816, 2020). "In order to further probe the biological function of TRIM2 in lung adenocarcinoma cells, we have studied TRIM2 expressions in six selected cell lines, including HNBE, H322, H1299, H460, H1703, and A549." (PMID 32536816, 2020). "In this study, our results suggested that the change of TRIM2 expression was closely related to the invasion, migration, proliferation, tumor stemness and tumor stem cell spheroidizing ability of lung adenocarcinoma cells." (PMID 32536816, 2020). "TRIM2 expression in lung adenocarcinoma tissues was higher than those in the paired normal tissues (P < 0.05)." (PMID 32536816, 2020). "Meanwhile, TRIM2 knockdown in A549 cells can restrain cell proliferation of lung adenocarcinoma cells in vitro." (PMID 32536816, 2020). "In this work, we have investigated the regulation of TRIM2 on lung adenocarcinoma cell migration and invasion in TRIM2 over-expression treated H322 cells and TRIM2 knockdown treated A549 cells." (PMID 32536816, 2020). "In this study, we have investigated the effect of TRIM2 expression changes on chemotherapy sensitivity of lung adenocarcinoma cells." (PMID 32536816, 2020). "Overexpression of TRIM2 or knockout of TRIM2 can affect the proliferation, migration and stemness of lung adenocarcinoma cells." (PMID 32536816, 2020). "Moreover TRIM2 knockdown significantly reduced the proliferation, colony formation, migration, and invasion of lung adenocarcinoma cells." (PMID 38893070, 2024). "TRIM2 is overexpressed in lung adenocarcinoma, which can regulate the degradation of Snail1 through ubiquitin protein pathway to promote the progression of lung adenocarcinoma." (PMID 37795365, 2023). "TRIM2 could enhance the proliferation, invasion, and migration of lung adenocarcinoma cells by regulating the ubiquitination-mediated degradation of Snail1." (PMID 36051486, 2022). "TRIM2 is highly expressed in lung adenocarcinoma, as measured by qRT–PCR and western blot analysis." (PMID 36051486, 2022). "However, previous studies have reported that TRIM2 mediates proliferation and metastasis of lung adenocarcinoma, by deubiquitinating and stabilizing Snail1 protein." (PMID 33714206, 2021). "Moreover, we have studied the effect of TRIM2 and Snail1 on chemotherapy sensitivity of lung adenocarcinoma cells." (PMID 32536816, 2020). "In summary, we demonstrated that high TRIM2 expression could be detected in lung adenocarcinoma tissues and cells." (PMID 32536816, 2020).
lung adenocarcinoma (continued). "In this study, we had tested the biological role of TRIM2 in lung adenocarcinoma." (PMID 32536816, 2020). "In summary, TRIM2 over-expression in H322 cells could promote cell proliferation of lung adenocarcinoma cells in vitro." (PMID 32536816, 2020). "In addition, TRIM2 can regulate Snail1 degradation in lung adenocarcinoma via ubiquitination pathway." (PMID 32536816, 2020). "Therefore, investigating the molecular mechanism of TRIM2 in the occurrence and development of lung adenocarcinoma provides an important clinical reference for the early diagnosis and prognosis evaluation of lung adenocarcinoma." (PMID 32536816, 2020). "Therefore, it is suggested that TRIM2 dysfunction may be one of the factors affecting the progression of lung adenocarcinoma." (PMID 32536816, 2020). "TRIM2 could promote the proliferation, migration, and invasion of lung adenocarcinoma." (PMID 32536816, 2020). "A high TRIM2 expression could be detected in lung adenocarcinoma tissues and cells." (PMID 32536816, 2020). "Therefore, TRIM2 may provide a potential target for the treatment of lung adenocarcinoma." (PMID 32536816, 2020). "Notably, Snail1 is a marker of epithelial–mesenchymal transition (EMT), revealing that TRIM2 and Snail can regulate EMT in lung adenocarcinoma." (PMID 36051486, 2022). "Meanwhile, western blot and qRT-PCR analysis indicated that TRIM2 expression in lung adenocarcinoma tissues was significantly higher than that in the paired normal tissues." (PMID 32536816, 2020). "Moreover, immunohistochemical staining analysis indicated that TRIM2 expression in lung adenocarcinoma tissue was significantly higher than that in the paired normal tissues." (PMID 32536816, 2020). "Therefore, our results revealed that TRIM2 and Snail can regulate EMT of lung adenocarcinoma." (PMID 32536816, 2020). "However, the function of TRIM2 in lung adenocarcinoma has not been reported." (PMID 32536816, 2020).
Ataxia (4 papers, 2018 to 2022). Ataxia refers to impaired coordination of voluntary muscle movement. "In a TRIM2-knockout mouse model, intra-axonal accumulation of NF-L secondary to TRIM2 deficiency caused progressive neurodegeneration that manifested as juvenile-onset tremor and ataxia." (PMID 29958463, 2018). "In particular, miR-181c was found to suppress Trim2 expression, providing a link to progressive neurodegeneration accompanied by juvenile-onset tremor and ataxia." (PMID 32698497, 2020). "Both the A and B strains developed ataxia and tremors, as had been previously reported for a TRIM2 knockout generated by insertional mutagenesis, although the phenotype in A strain mice was more severe." (PMID 30726215, 2019). "Knockout mice deficient in TRIM2 were reported to develop NEFL buildup in central nervous system axons accompanied by progressive neurodegeneration, tremor, and ataxia, which was attributed to an inability to degrade NEFL." (PMID 30726215, 2019). "Moreover, as a downstream target of miR-181c, TRIM2 expression can be inhibited by miR-181c, an event closely related to the development of progressive neurodegeneration with juvenile tremor and ataxia." (PMID 36051486, 2022). "Moreover, Trim2-deficient mice showed an accumulation of neurofilament light chain (NEFL) in neuronal structures, which causes axonopathy, progressive neurodegeneration, and juvenile onset of tremor and ataxia." (PMID 32698497, 2020).
clear cell renal cell carcinoma (3 papers, 2019 to 2024). "LINC01535 affects clear cell renal cell carcinoma progression by mediating PI3K/Akt signaling through the LINC01535/miR–146b-5p/TRIM2 axis, corresponding to the LINC01535/miR-146b-5p binding pair predicted in this study." (PMID 37325630, 2023). "However, some previous reports showed opposite results with the expression of TRIM2, which is downregulated in clear cell renal cell carcinoma, affecting cell proliferation and migration, and also showed opposite results regarding patients’ survival." (PMID 38893070, 2024).
Cognitive impairment (3 papers, 2017 to 2025). Abnormal cognition is characterized by deficits in thinking, reasoning, or remembering. "A recent in vivo study also demonstrated that microRNA-181c, through its modulation of TRIM2, can attenuate cognitive impairment in rats induced by chronic cerebral ischemia." (PMID 29958463, 2018). "Fang and colleagues showed that miR-181c targeting TRIM2 ameliorates cognitive impairment induced by chronic cerebral hypoperfusion in rats." (PMID 28806967, 2017).
ischemia (3 papers, 2018 to 2025). A hypoperfusion of the BLOOD through an organ or tissue caused by a PATHOLOGIC CONSTRICTION or obstruction of its BLOOD VESSELS, or an absence of BLOOD CIRCULATION. "TRIM2 protects male mice from intestinal ischemia-reperfusion injury by marking the pro-death BNIP3 protein for degradation, revealing a potential therapeutic target." (PMID 40883557, 2025). "Future studies exploring TRIM2’s regulatory network or pharmacological enhancers of its activity could unlock strategies for mitigating intestinal ischemia/reperfusion injury." (PMID 40883557, 2025). "It is conceivable that TRIM2 may well play a similar role in mediating the angiogenic response to ischemia downstream of HDL." (PMID 29958463, 2018).
lung carcinoma (3 papers, 2020 to 2024). "TRIM2 could aggravate cell proliferation, invasion, and migration in lung cancer by regulating Snail1 ubiquitylation degradation." (PMID 32536816, 2020).